OPA1 (OPA1 mitochondrial dynamin like GTPase)
Diseases named in the same sentence as OPA1 in open-access papers (continued):
Sharing a sentence is not in itself a finding about the gene and the disease.
neurodegenerative disease (23 papers, 2010 to 2025). A disorder of the central nervous system characterized by gradual and progressive loss of neural tissue and neurologic function. "Previous studies reported that mutations in human Mfn2 or OPA1 were related to neurodegenerative diseases." (PMID 41299984, 2025). "Disruptions in mitochondrial function, such as those seen with mutations in the MFN2 and OPA1 genes, contribute to neurodegenerative diseases like CMT2A and ADOA." (PMID 40149969, 2025). "In summary, we show that mitochondrial dysfunction typically found in neurodegenerative diseases (through Opa1 loss) leads to neurogenesis impairment which subsequently causes learning and memory deficits." (PMID 38757355, 2024). "Mutations or knockdown of the MICOS proteins, ATP synthase, and the dynamin-related GTPase OPA1 are associated with severe defects in cristae morphology leading to a number of cardiovascular and neurodegenerative diseases." (PMID 31163678, 2019). "In this context, proteins that directly modulate mitochondrial fusion have been found mutated in neurodegenerative diseases like Charcot-Marie-Tooth 2A (Mitofusin-2 (Mfn2);) or autosomal-dominant optic nerve atrophy (optic atrophy protein 1 (OPA1);)." (PMID 20064504, 2010). "Since Opa1 plays a critical role in the regulation of mitochondrial structure and function and is implicated in a number of neurodegenerative diseases, we generated an Opa1‐inducible knockout in adult NSCs as a model to study the effects of mitochondrial dysfunction on adult neurogenesis." (PMID 38757355, 2024). "Findings from OPA1-mutant iPSC-derived disease models can advance the understanding of the pathological mechanisms underlying DOA as well as provide important insights into other neurodegenerative diseases that share common metabolic deficiencies with DOA." (PMID 37745862, 2023). "A better understanding of why specific neuronal populations are impacted by OPA1 variants and the specific downstream effects of energy deficit on neuronal survival could have broader significance for other neurodegenerative diseases associated with RGC loss." (PMID 35652445, 2022). "The cited evidence suggests that OPA1‐mediated mitochondrial dysfunction is involved in the pathogenesis of various neurodegenerative diseases." (PMID 38267829, 2024). "Studies have pointed out that inhibition of OPA1 enhances the progression of neurodegenerative diseases, and OPA-1 regulates apoptosis resistance of OXPHOS IL-17-producing CD4 T cells by regulating mitochondrial fusion and limiting mitophagy." (PMID 37434203, 2023). "The importance of mitochondrial dynamics in the pathogenesis of neurodegenerative diseases has been increasingly unraveled after the identification of several key fusion and fission regulators such as Drp1, OPA1, and mitofusins." (PMID 28379197, 2017). "The overexpression of edited miR-497–5p may aggravate neurodegenerative diseases by inhibiting genes such as OPA1." (PMID 41446042, 2025). "OPA1 R445H neurons demonstrated upregulated SOCE which could reflect an attempt to refill ER calcium stores, a pathway that has been described in other neurodegenerative disease models." (PMID 39948685, 2025).
myopathy (15 papers, 2009 to 2025). A disease of the muscle in which the muscle fibers do not function properly. "Although MFN1 and OPA1 deficiency can cause inflammatory myopathy in mouse muscle KO models, the role of mtDNA-mediated inflammation in MFN2 pathology has not been fully explored." (PMID 40175090, 2025). "OPA1 transgenic mice are protected from acute muscle loss induced by denervation as well as from chronic muscle loss in a model of myopathy caused by muscle-specific deletion of the mitochondrial subunit COX15." (PMID 33078210, 2021). "OPA1 heterozygous missense recessive mutations cause DOA characterized by an aspecific myopathy with mitochondrial features." (PMID 33078210, 2021). "However, more recent work linking MFN1 and OPA1 muscle deficiency to inflammation-mediated myopathy showed that blocking the inflammation was protective in these models, arguing for a key role of inflammation in the muscle pathology caused by impaired mitochondrial fusion." (PMID 40175090, 2025). "Arguing that activation of TLR9-mediated inflammation is a general response to loss of mitochondrial fusion, loss of the inner mitochondrial membrane fusion protein OPA1 in muscle leads to TLR9-mediated NF‐κB activation (but not cGAS-STING), where it also drives an inflammatory myopathy." (PMID 40175090, 2025).
peripheral neuropathy (15 papers, 2009 to 2025). A disorder affecting the peripheral nervous system. "Here, we focus specifically on MFN2 and OPA1, as pathogenic variants in these genes are clearly related to a peripheral neuropathy phenotype." (PMID 33810506, 2021). "Though OPA1 is expressed in multiple systems, OPA1 dysfunction diseases are all related to peripheric neuropathy." (PMID 34621753, 2021). "Meanwhile, specific pathogenic variants in a number of essential fusion (OPA1 and MFN2) and fission (DRP1) proteins lead to various neuronal pathologies in humans, such as optic atrophy, peripheral neuropathy, and encephalopathy." (PMID 33810506, 2021). "As a comprehensive understanding of exactly how OPA1 dysfunction causes these varying phenotypes is lacking, the mechanism responsible for peripheral neuropathy specifically remains uncertain." (PMID 33810506, 2021). "Based on the largest described series of OPA1-related ADOA, peripheral neuropathy is present in approximately 30% of patients, and is axonal with predominant sensory involvement." (PMID 33810506, 2021).
neurological disorders (11 papers, 2016 to 2024). "Inactivating OPA1 mutations have been associated with human neurological disorders, and is driven by an altered transcriptional circuitry in neural stem cells." (PMID 39516459, 2024). "Pathogenic variants of OPA1, which encodes a dynamin GTPase involved in mitochondrial fusion, are responsible for a spectrum of neurological disorders sharing optic nerve atrophy and visual impairment." (PMID 30988455, 2019). "Similarly, diminished lysine catabolism to glutamate in other neurological disorders appears to cause the synaptic dysfunction in Opa1-deficient patients." (PMID 32751190, 2020). "PHBs can prevent apoptosis, inflammation, mitochondrial dysfunction, and autophagy in neurological disorders through different molecules and pathways, such as OPA-1, PINK1/Parkin, IL6/STAT3, Tau, NO, LC3, and TDP43." (PMID 35847581, 2022). "Unlike OPA1, DRP1 plays an important role in the modulation of mitochondrial fission, and involves various neurological diseases." (PMID 27242436, 2016).
heart disease (9 papers, 2015 to 2025). "To date, many studies have confirmed that the fusion and fission dynamins of cardiac mitochondria, in particular the GTPase dependent dynamins (DRP1, MFN1, MFN2, OPA1) are associated with the occurrence and development of various heart diseases." (PMID 34660720, 2021). "We posit that precise modulation of the activities of Drp1, Mfn1/2, and OPA1 presents significant potential for the treatment of cardiac diseases." (PMID 41000071, 2025). "In recent years, increasing evidence has shown that OPA1, which plays a crucial role in regulating mitochondrial fusion, has protective effects in various cardiac diseases, especially in I/R." (PMID 32934760, 2020). "Also in this case, additional studies in humans are required to extend the knowledge on OPA1 regulation to move towards the development of novel therapies for OPA1-specific cardiac disease progression." (PMID 37726810, 2023). "However, it is important to take into consideration the pleiotropic roles of the mitochondrial shaping proteins especially the fusion proteins, Mfn2 and OPA1, when targeting the mitochondrial shaping proteins as a treatment for cardiac disease." (PMID 28190190, 2017). "Downregulation or post-translational modification of these fusion proteins have been confirmed as related to a variety of heart diseases, however, the specific mechanisms through which MFN1, MFN2, and OPA1 function in cardiomyocytes require further research." (PMID 34660720, 2021). "As mitochondrial fission and fusion are primarily regulated by mitochondrial dynamins in a GTPase-dependent manner, GTPase-dependent mitochondrial fusion (MFN1, MFN2, and OPA1) and fission (DRP1) proteins, which are abundant in the adult heart, can also be regulated in heart diseases." (PMID 34660720, 2021).
infection (9 papers, 2013 to 2024). The state of being infected such as from the introduction of a foreign agent such as serum, vaccine, antigenic substance or organism. "Altogether, our results revealed that SIRT3 displays infection-induced changes in its association with the fusion factor OPA1, which are temporally dynamic and that match K834 acetylation levels on this substrate." (PMID 33857259, 2021). "Opa1 protein in KPO cells is almost completely undetectable 3 days after AdCre infection, which allows determination of the acute effects of Opa1 deletion." (PMID 36516772, 2022). "This suggests that the host cell responds in defense by promoting SIRT3-mediated OPA1 deacetylation, and this is then counteracted by the virus later in infection." (PMID 33857259, 2021). "We find that OPA1 knockdown and over-expression have an impact on mitochondrial morphology and HCMV viral protein levels at 24 hpi, suggesting that the SIRT3 substrate OPA1 exerts a virus restriction function early in infection." (PMID 33857259, 2021). "Conversely, infection increased OPA1 signal at the mitochondria, suggesting a coalescence of the protein at this compartment, OPA1 being a key protein in mitochondrial fusion." (PMID 33596274, 2021). "This OPA1 acetylation was dynamic during infection, decreasing at 24 hpi, then returning to its original levels, and slightly increasing later in infection." (PMID 33857259, 2021). "We discover that OPA1 knockdown leads to mitochondrial fission during infection and elevated virus titers, while OPA1 overexpression resulted in reduced virus titers." (PMID 33857259, 2021). "AdCre infection of this cell line deletes Drp1 and Opa1 within 3 days of infection." (PMID 36516772, 2022). "Our acetylome analysis during infection pointed to another OPA1 acetylated residue, K834." (PMID 33857259, 2021). "We next asked whether the OPA1 acetylation status specifically contributes to this observed impact on mitochondrial morphology during infection and virus production." (PMID 33857259, 2021). "Specifically, OPA1-KD resulted in decreased mitochondrial area and increased percentage of mitochondrial fragments, phenotypes already evident at an early infection time point (24 hpi) and maintained later in infection (72 hpi)." (PMID 33857259, 2021). "We constructed OPA1 mutants with a charge mimic of the unmodified residue (K931R) and a constitutively acetylated mimic (K931Q) and assessed their impact on mitochondria structure during infection." (PMID 33857259, 2021). "We also determined that inhibition of mitochondrial fusion by Opa1 knockdown in INS1 cells resulted in increased subcellular heterogeneity of MitoTimer age profile (P < 0.05, n = 17 cells for control, 27 cells for Opa1 knockdown from two independent infection procedures)." (PMID 24149000, 2013). "Although it has not been studied extensively, it is possible that stress-induced mitochondrial hyperfusion—dependent on L-OPA1, MFN1, and SLP-2 —is mediated through OPA1 PTMs during infection with viruses that elongate mitochondria, such as Dengue virus." (PMID 37238738, 2023). "We did not detect any change in OPA1 isoforms expression following infection even if OPA1 total amount is decreased." (PMID 33596274, 2021). "This is evidenced by the increased mitochondrial area and filamentous network and the decreased percentage of fragmented mitochondria at both early (24 hpi) and late (72 hpi) stages of infection, in conjunction with decreased HCMV titer (control versus OPA1 WT)." (PMID 33857259, 2021). "Our finding that SIRT3 displays reduced interactions with its substrate OPA1 late in infection, and that active SIRT3 and OPA1 both inhibit virus production, led us to ask whether the SIRT3 deacetylase activity by itself has the ability to impact mitochondrial structure." (PMID 33857259, 2021).
infection (continued). "To relatively position MIC60 and OPA1 in the pathway controlling CJ biogenesis, we completed our epistatic analysis by measuring the same parameters of CJ number and CLW in sorted GFP+ and RFP+ cells upon infection with the GFP-expressing adenoviruses and MIC60-V5/mtRFP cotransfection." (PMID 27974214, 2016). "In contrast, immunoreactive levels of FOXK2, OPA1, MFF, and PHB1 generally were preserved in the majority of Fbxo24+/− mice regardless of infection." (PMID 38735474, 2024).
cardiovascular diseases (7 papers, 2018 to 2025). "Optic atrophy 1 (OPA1) is a key regulator of mitochondrial fusion, and the AMP-activated protein kinase (AMPK)/OPA1 pathway is associated with mitochondrial fusion/mitophagy during cardiovascular disease." (PMID 32377301, 2020). "Recent studies suggested that OPA1 participates in the development of cardiovascular diseases." (PMID 35663194, 2022). "Thus, leptin targeting the GSK3/OMA1/OPA1 signaling pathway can optimize hMSCs therapy for cardiovascular diseases such as MI." (PMID 29748581, 2018). "Moreover, both OPA1 and Mfn2 were reported to be decreased regarding cardiovascular disease, but in our study, both biomarkers were not altered in the nontreated vitamin C groups." (PMID 34831251, 2021).
metabolic disease (4 papers, 2019 to 2025). A congenital disorder (due to inherited enzyme abnormality) or acquired (due to failure of a metabolically important organ) disorder resulting from an abnormal metabolic process. "Interestingly, imbalanced mitochondrial metabolism induced by mitochondrial proteins (especially mitofusins, Opa1, and Drp1) in various tissues has been implicated in the pathology of metabolic diseases." (PMID 31551926, 2019). "The decreased levels of Sam50 and OPA1 proteins suggest their potential as targets for correcting mitochondrial dysfunction in metabolic disorders." (PMID 41369368, 2025). "FGF21 and GDF15 act synergistically to maintain glucose homeostasis and promote resistance to DIO in mice lacking OPA1 in BAT, highlighting the potential of combined therapies using FGF21 and GDF15 for the treatment of metabolic disorders." (PMID 40897647, 2025).
kidney diseases (3 papers, 2019 to 2021). "Comparison of the Chow and HFD groups with regard to the levels of blood glucose, sizes of the kidneys and glomerulus, and levels of 8‐OHdG, GPX1, F4/80, and OPA1 indicated the successful development of NASH‐related kidney diseases." (PMID 31561285, 2019). "A large number of studies indicated that OPA1 and Mfn 2 may suffer post-transcriptional and translational modifications, reducing their expression in kidney diseases." (PMID 34831251, 2021).
retinal disorder (3 papers, 2009 to 2025). Any disease or disorder of the retina. "Heterozygous mutation of OPA1 has predominantly been associated with retinal disorders, but recent studies indicate that it disrupts function of other organs." (PMID 19718456, 2009). "These retinopathies could result from specific mitochondrial variants, including the m.3243G>A variant, and mutations in the fusion/mitochondrial shaping protein OPA1, encoded with a nuclear gene on chromosome 3q29." (PMID 38001864, 2023).
Genetic disorders (2 papers, 2017 to 2025). "Mutations in DRPs such as OPA1, Mitofusin2, Atlastin, and Drp1 have been identified as the causes of many genetic disorders in humans." (PMID 28081268, 2017).
neuromuscular disease (1 paper, 2015). "Mutations in OPA1 (optic atrophy 1) caused multisystemic neuromuscular disease in 8 adults in addition to visual failure (minimum prevalence = 0.4 × 10−5, 95% CI = 0.2–0.7 × 10−5)." (PMID 25652200, 2015).
OPA1 also shares sentences with these, for which no sentence is quoted: axonal neuropathy (4 papers); primary open angle glaucoma (4); cerebellar ataxia (3); CHARGE syndrome (3); colorectal cancer (3); Leigh syndrome (3); mitochondrial encephalomyopathy (3); Cachexia (2); depression (2); esophageal cancer (2); MERRF (2); ptosis (2); retinitis pigmentosa (2); sensory ataxia (2); spastic ataxia (2); Spastic paraparesis (2); Stickler syndrome (2); -motor polyneuropathy (1); -phosphoglycerate dehydrogenase deficiency (1); 3-methylglutaconic aciduria (1); 3-methylglutaconyl-CoA hydratase deficiency (1); abetalipoproteinemia (1); acute lung injury (1); acute lymphoblastic leukemia (1); adenoma (1); age-related hearing impairments (1); amblyopia (1); aneurysm (1); anterior ischemic optic neuropathy (1); Areflexia (1).
A further 116 diseases each share a sentence with OPA1 in 1 paper.